STAT3 (signal transducer and activator of transcription 3)
Diseases named in the same sentence as STAT3 in open-access papers (continued):
Sharing a sentence is not in itself a finding about the gene and the disease.
osteoporosis (continued). "Finally, STAT3-mediated cell–cell interactions involve a wide range of nonbone cells, which enlarges the window to show how these factors interact with bone cells during osteoporosis and should be examined in future studies." (PMID 35879773, 2022). "Here we show the evidence that STAT3 deficiency in bone marrow mesenchymal stem cells (BMSCs) or pre-osteoblasts, but not in osteoclasts, induces craniofacial deformity, osteoporosis, and spontaneous bone fractures, resembling the cranial bone phenotypes of AD-HIES patients." (PMID 34824272, 2021). "In summary, NTZ could inhibit osteoclastogenesis and bone loss through modulation of the receptor activator of NF-κB ligand-induced STAT3-NFATc1 signaling pathway, which might be a potential alternative treatment regimen against bone destruction-related diseases including osteoporosis." (PMID 34955850, 2021). "Thus, the effects of NHA and HAD on RANKL-induced osteoclastogenesis and on OVX-induced osteoporosis in mice could be explained by the inhibition of IL-6/STAT3." (PMID 34833909, 2021). "In summary, the JAK/STAT3 and PI3K/AKT pathways are crucial in osteoporosis and have complex interactions with each other." (PMID 40332238, 2025). "Differential expression analysis in osteoporosis and sarcopenia datasets revealed that seven biomarkers—BCL6, DDIT4, FOXO1, IRS1, NFKBIA, PGK1, and STAT3—were differentially expressed in the independent osteoporosis dataset GSE84500." (PMID 41282482, 2025). "This study uncovers key molecular links between osteoporosis and sarcopenia, highlighting DDIT4, FOXO1, and STAT3 as shared biomarkers." (PMID 41282482, 2025). "In summary, we revealed that BCI inhibited RANKL-mediated osteoclastogenesis by restraining STAT3 activity and NF-κB–NFATc1 signaling in vitro and ameliorating OVX-induced osteoporosis in vivo." (PMID 34803714, 2021). "Taken together, the deletion of Stat3 in pre-osteoblasts induced AD-HIES-related skeletal deformities, such as craniofacial deformities and osteoporosis." (PMID 34824272, 2021). "Our findings also offer an innovative aim for therapy of senile osteoporosis and evidence to prompt additional investigation of the interaction between RPN2 and the JAK1/STAT3 pathway in hBMSC osteogenic differentiation." (PMID 31743606, 2020). "Therefore, a distinct signaling, including STAT3/miR-7-5p/CRY2, has been revealed during osteoblast differentiation, which may provide a potential therapeutic strategy against disorders associated with osteoporosis." (PMID 31982773, 2020). "Bazedoxifene, a selective estrogene receptor modulator clinically available for the treatment of osteoporosis, has been shown to be an effective GP130/STAT3 signaling inhibitor through in vitro and small animal studies." (PMID 31139333, 2019). "Additionally, PPARG, PTGS2, IL6, STAT3, and JUN have been reported to play important roles in the development of osteoporosis." (PMID 40299567, 2025). "Given the effect of STAT3 on bone homeostasis, we believe that BAZ1B may also play an important role in osteoporosis." (PMID 38650009, 2024). "On the other hand, deletion of Stat3 either in BMSCs or pre-osteoblasts induced exhibited a series of AD-HIES-like skeletal defects, such as craniofacial malformations, osteoporosis, and bone fragility through impaired osteogenesis as well as reduced osteoblast differentiation." (PMID 34824272, 2021). "Besides, STAT3 and SPI1 may also affect heterotopic ossification and osteoporosis in AS through regulating NKT and TH1 cells differentiation." (PMID 35065610, 2022). "Furthermore, other abnormalities associated with STAT3-HIES, including coarse facies and osteoporosis, were reported to have resolved, and there was no symptomatic development of STAT3-HIES-associated vasculopathy, although it is not clear if any screening was performed." (PMID 33523338, 2021).
osteoporosis (continued). "Herein, we reported that the mice with Stat3 deletion in osteoblasts, but not in osteoclasts, induced AD-HIES-like skeletal defects, including craniofacial malformation, osteoporosis, and spontaneous bone fracture." (PMID 34824272, 2021). "The deletion of Stat3 in MSC and pre-osteoblasts leads to Autosomal dominant hyperimmunoglobulin E syndrome (AD-HIES)-like cranial deformities, significant reduction in cortical bone thickness and systemic osteoporosis, but not osteoclasts." (PMID 35548357, 2022).
steatosis (45 papers, 2012 to 2025). Increased lipid within the cytoplasm of cells. "The resistance to steatosis was linked to an increase in inflammation-associated hepatic IL-6/STAT3 activation, which in turn caused the liver to downregulate lipogenic genes and upregulate genes linked to fatty acid oxidation." (PMID 38535313, 2024). "ROS with NO induces steatosis (through lipid peroxides) and oncogenesis (through DNA mutations and STAT3 activation), leading to acute hepatocyte damage (via production of STAT3)." (PMID 36187761, 2022). "Specifically, the deletion of IL-10 results in IL-6/STAT3 mediated inflammatory response in the liver, decreasing steatosis." (PMID 41514930, 2025). "In IL-10(−/−) animals, further deletions of IL-6 or hepatic STAT3 increased the inflammatory response in the liver but reversed steatosis and hepatocellular damage." (PMID 38535313, 2024). "Loss of m6A writer protein WTAP or METTL3 in hepatocytes enhances hepatic steatosis, inflammation, and activation of STAT3 and ERK signaling pathways, which exacerbates the course of DEN-induced HCC." (PMID 37777158, 2023). "Previous study demonstrated that hepatocyte-specific STAT3 deletion exacerbates alcohol-induced steatosis and liver injury." (PMID 34262465, 2021). "Administration of rmIL-22 or IL-22 adenovirus activates hepatic STAT3 signaling, therefore alleviating alcohol-induced hepatitis and steatosis." (PMID 34944732, 2021). "STAT3 signaling is related to liver inflammation, injury, steatosis, fibrosis, and HCC, and it is overexpressed in patients with NASH and HCC." (PMID 33785040, 2021). "For instance, treatment with IL-6 ameliorated fatty liver by inducing STAT3 phosphorylation in ob/ob and HFD- induced obese mice, while deletion of IL-6 or hepatic STAT3 resulted in steatosis and hepatocellular damage in IL-10 knockout mice." (PMID 30038584, 2018). "The present study investigates the role of a miRNAs-phospho-STAT3 pathway in the induction of liver vesicular steatosis in an in vitro model, represented by hepatic differentiated HepaRG cells treated with sodium oleate, fatty dHepaRG." (PMID 30206377, 2018). "It has been implicated in sorting of glycoproteins, quality control of endoplasmic reticular proteins, antigen processing by MHC proteins, control of STAT3 function, induction of apoptosis, and suppression of steatosis." (PMID 22545783, 2012). "Therapeutically, the study provides proof of concept for STAT3 inhibition (TTI-101) as being effective to ameliorate steatosis, inflammation, and fibrosis in DKO mice, confirming STAT3 as a druggable master regulator downstream of BRUCE/PTEN in murine MASH models." (PMID 41381438, 2025). "Additionally, its receptor OSMRβ improves obesity-induced hepatic IR and steatosis by activating the JAK2/STAT3 signaling pathway." (PMID 40969371, 2025). "This study identifies BRUCE as a critical co-suppressor of MASLD/MASH, working synergistically with PTEN to regulate MASLD/MASH progression via a STAT3 central signaling hub that orchestrates the transition from steatosis to inflammatory fibrosis, while providing rigorous mechanistic insights." (PMID 41381438, 2025). "Treatment with IL-22 ameliorated steatosis and liver damage by the upregulation of anti-apoptotic and anti-oxidative genes, and the vial downregulation of lipogenic genes in hepatocytes was mediated by activation of STAT3-signaling cascade." (PMID 39200991, 2024). "Enhanced expression of leptin-induced hepatic CD14 may increase hepatic responsiveness to even low levels of gut microbiota-derived endotoxins, which may prompt the progression of simple steatosis to NASH via STAT3 signaling." (PMID 34777261, 2021). "In chow-fed mice Leptin increased hepatic expression of CD14 via STAT3 signaling and hyperreactivity against low-dose LPS without steatosis, while leptin-deficient ob/ob mice with severe steatosis had a marked decrease in hepatic CD14." (PMID 32823983, 2020).
steatosis (continued). "Previous studies demonstrated that STAT3 signaling played a very important role in liver injury, hepatic inflammation, steatosis, regeneration, and neutrophil trafficking, and acute ethanol intake could activate STAT3 signaling in monocytes." (PMID 31931878, 2020). "In order to identify, at a genome-wide level, genes potentially regulated by phospho-STAT3 during the pathogenesis of steatosis, we performed a Chromatin Immunoprecipitation Sequencing (ChIP-seq) analysis on fatty dHepaRG cells using a phosphoTyr705-STAT3-specific antibody." (PMID 30206377, 2018). "Likewise, in the present study, we found that chronic treatment with rIL-6 in WT DIO mice increased hepatic Stat3 phosphorylation and exacerbated steatosis." (PMID 27333268, 2016). "High level of ROS could be induced by NS5A in transgenic mice, cooperated with upregulation of NF-κB and STAT3, which promote steatosis and HCC." (PMID 27696294, 2016). "Inhibition of the miR-21 expression alleviated steatosis by upregulation of the key regulators of lipid metabolism, such as hepatocyte nuclear factor 4 alpha (Hnf4a), forkhead box transcription factors (Foxa2 and Foxo1), Ppara, and the signal transducer and activator of transcription 3 (Stat3)." (PMID 35052690, 2021). "Chow-fed control mice did not have a similar effect and leptin increased hepatic expression of CD14 via STAT3 signaling and hyperreactivity against low-dose LPS without steatosis, while leptin-deficient ob/ob mice with severe steatosis had a marked decrease in hepatic CD14." (PMID 35052763, 2021). "Thus, enhanced expression of hepatic CD14 by leptin may increase hepatic responsiveness to gut microbiota-derived endotoxins even at low levels, resulting in the progression from simple steatosis to NASH via STAT3 signaling." (PMID 34360923, 2021). "This upregulation enhances ARG2 expression through the STAT3 signaling pathway, leading to increased fatty acid oxidation (FAO) mediated by OPN, which effectively mitigates steatosis." (PMID 40969371, 2025). "Taken together, we provide evidence that OF exhibits the anti‐HCC, anti‐steatosis, and anti‐fibrosis effect for liver in zebrafish models, and the anti‐cancer potential of OF attributed to the binding to ASGR and activation of STAT3/HNF4A signaling." (PMID 33377648, 2020). "Therefore, we hypothesized that hepatic STAT3 signaling was closely related to liver injury, steatosis and inflammation, and hepatic neutrophil and monocyte/macrophage infiltration in AH, and hepatic STAT3 signaling might be a therapeutic target of MSC treatment." (PMID 31931878, 2020). "Stat5/3loxP/loxP mice crossed to a transgenic line expressing the Cre recombinase in hepatocytes showed deletion of STAT3 and STAT5A/B in the liver and developed steatosis at the age of eight weeks." (PMID 31443474, 2019). "In that case, the IL-6 administration restored the hepatic Stat3 phosphorylation under a HFD, as well as up-regulating the expression of the lipogenic enzymes and worsening the steatosis." (PMID 27333268, 2016). "Coincident with an alleviation of hepatic steatosis, we computationally detected the downregulation of IL-6/JAK/STAT3 signaling and the inflammatory response (e.g., Tlr8, Mlkl), together with impaired EMT (Lgals1) in the liver, while the expression of genes related to mTOR was enhanced by LY." (PMID 35737463, 2022). "SIRT1 may improve NAFLD by regulating ROS, PGC-1α, SREBP-1c, FoxO1/3, STAT3, and AMPK to restore mitochondrial function and reduce steatosis of the liver." (PMID 36008973, 2022). "Interestingly, in this study the authors found an uncoupling of steatosis and carcinogenesis; while STAT1 activation propagated liver steatosis, STAT3 mediated HCC development." (PMID 35269812, 2022). "Whereas other steatosis-promoting inflammatory cytokines, such as TNF-α and IFN-γ, are also increased in mice lacking IL-10, their effect is masked by IL-6/STAT3 anti-lipogenic properties." (PMID 41514930, 2025).
steatosis (continued). "Stat5/3Δhep/Δhep mice exhibited a marked reduction of STAT3, STAT5A and STAT5B proteins in the liver and developed steatosis, a phenotype that resembles mice lacking Stat5a/b in hepatocytes." (PMID 31443474, 2019). "The HFD-fed IL-6−/− mice showed severe steatosis, no changes in CPT1 levels or AMPK activity, no increase in STAT3 amounts, inactivated STAT3, and marked downregulation of the expression of acetyl-CoA carboxylase (ACCα/β), FAS and SCD1." (PMID 26035386, 2015). "Leptin and STAT3 signaling increased the responsiveness to gut-derived, low-dose bacterial endotoxin even in the healthy liver via an increase in CD14-positive Kupffer cells, regardless of the presence of steatosis." (PMID 34360923, 2021).
colorectal tumor (44 papers, 2010 to 2025). "In another study, FGFR2 (hub gene in Subnetwork 7) is reported to promote the PD-L1 expression via the JAK/STAT3 signaling in colorectal tumors and associated with disease progression and poor survival." (PMID 34790220, 2021). "Notably, low MLKL expression in human colorectal tumors, which enhanced STAT3 activation, was associated with decreased overall survival." (PMID 33767595, 2021). "IL-6, secreted by MSCs, stimulates the growth of colorectal tumor-initiating cells and encourages tumor development through STAT3 signaling." (PMID 40534879, 2025). "In conclusion, MISP enhances colorectal tumorigenesis through its interaction with OIP5 and stimulates colorectal tumor growth by upregulating the levels of phosphorylated STAT3 in the JAK2-STAT3 signaling pathway." (PMID 38474305, 2024). "has shown that inhibition of TRIB3 signalling increases CD8+ T cell accumulation in colorectal tumours in a similar STAT3/STAT1/CXCL10 dependent mechanism." (PMID 39165364, 2024). "Interleukin-6-mediated activation of STAT3 in fibroblasts played a key role in driving colorectal tumors." (PMID 35211500, 2022). "Given our findings that loss of MLKL increased activation of STAT3 in spontaneous intestinal tumorigenesis, we further examined the potential correlation between MLKL expression and STAT3 activation in human colorectal tumor samples." (PMID 33767595, 2021). "Activation of IL-6/p-STAT3/c-MYC signaling was demonstrated to enhance colorectal tumor growth in a TLR4-dependent manner." (PMID 34898475, 2021). "We further found that reduced MLKL expression was correlated with poor prognosis and STAT3 hyperactivation in colorectal tumors." (PMID 33767595, 2021). "Persistent activation of STAT3 and cyclin D1 overexpression also contribute to enhanced cellular proliferation in colorectal tumor growth." (PMID 32024285, 2020). "Colorectal tumors often show a diffuse infiltrate of cytokine‐producing immune/inflammatory cells that contribute to disease progression in part via the activation of STAT3 signaling in transformed epithelial cells." (PMID 31361391, 2019). "The oncogenic role of IL6R in mediation of colorectal tumour invasion via activation of EMT was demonstrated though modulation of the IL-6R/STAT3/miR-34a feedback loop." (PMID 30857282, 2019). "TNF-α and IL-6 are core cytokines in the colorectal tumor promotion by activating NF-κB signaling pathways and STAT3." (PMID 30157754, 2018). "Several factors involved in NF-kappa B, STAT3, Notch or Wnt pathways have been previously shown to play a role in radioresistance of colorectal tumours." (PMID 28938581, 2017). "The continuous evidence of recent years has convinced us that IL-6/JAK/STAT3 pathway can play a definitive role in the transformation from inflammation to cancer for colorectum tumor." (PMID 28061445, 2017). "The results of the immunostaining for STAT3 and β-catenin in a series of 44 primary colorectal tumours." (PMID 25348333, 2014). "Notably, the low expression of MLKL in human colorectal tumors enhances the activation of the signal transducer and activator of transcription 3 (STAT3)." (PMID 37238692, 2023). "Thus tRXRα expression in myeloid cells can induce IL-6 expression and STAT3 activation in colorectal tumor." (PMID 30931933, 2019). "Patients with CRC often exhibit persistently activated STAT3, which could protect cells from apoptotic stimuli and promote cell-cycle progression in colorectal tumors." (PMID 28331523, 2017). "Interestingly few other studies also reported that activated STAT-3 was involved in β-catenin nuclear accumulation in human colorectal tumors." (PMID 25869100, 2015). "Thus, STAT3 determined cell survival in EGFR-positive colorectal tumors." (PMID 30068339, 2018).
colorectal tumor (continued). "Therefore, the detection of STAT3 expression in colorectal tumors may be a useful predictor of the degree of malignancy and prognosis, and may provide a novel target for cancer treatment." (PMID 23170117, 2012). "Our results showed that α-hederin treatment significantly inhibited colorectal tumor formation and growth by inhibiting p38 MAPK/STAT3 inflammatory-cancer transformation pathway and attenuating oxidative stress." (PMID 41281755, 2025). "Utilizing the TIMER2.0 database, overexpression of PDIA3 in colorectal tumors was initially identified, and further confirmed through GEO database analysis, establishing a strong correlation between PDIA3, STAT3, and CD274." (PMID 38761176, 2024). "We also report a positive correlation between STAT3 and IRF9 protein abundance in primary colorectal tumour samples and cell lines." (PMID 30679726, 2019). "To understand whether these and other inflammatory pathways are dysregulated in Nlrp12–/– colorectal tumors, we measured the activation of NF-κB, ERK, JNK, STAT3, and AKT in tumors collected on day 80 after AOM/DSS treatment." (PMID 37581937, 2023). "Furthermore, we saw that there was a negative relationship between MLKL and the STAT3 target genes expression in colorectal tumors." (PMID 33767595, 2021). "Notably, although NF-κB and MAPK pathways were not dysregulated, there was increased STAT3 activation in colorectal tumors of Nlrp12–/– mice, which could be secondary to increased β-catenin." (PMID 37581937, 2023).